LAMTOR4 (late endosomal/lysosomal adaptor, MAPK and MTOR activator 4)
Description:
As part of the Ragulator complex it is involved in amino acid sensing and activation of mTORC1, a signaling complex promoting cell growth in response to growth factors, energy levels, and amino acids. Activated by amino acids through a mechanism involving the lysosomal V-ATPase, the Ragulator plays a dual role for the small GTPases Rag (RagA/RRAGA, RagB/RRAGB, RagC/RRAGC and/or RagD/RRAGD): it (1) acts as a guanine nucleotide exchange factor (GEF), activating the small GTPases Rag and (2) mediates recruitment of Rag GTPases to the lysosome membrane. Activated Ragulator and Rag GTPases function as a scaffold recruiting mTORC1 to lysosomes where it is in turn activated.
Synonyms: C7orf59
Tractability: Small molecule: a structure with a bound ligand is known. PROTAC: ubiquitination databases record sites on it; its protein half-life has been measured.
Gene: Protein-coding gene on chromosome 7 (100,148,912 to 100,155,944, forward strand). Ensembl gene ENSG00000188186.
Subcellular location: Lysosome
Subcellular location (Human Protein Atlas): Lysosomes; Golgi apparatus
Pathways (Reactome):
Signal Transduction: Energy dependent regulation of mTOR by LKB1-AMPK; MTOR signalling; Regulation of PTEN gene transcription; mTORC1-mediated signalling
Autophagy: Macroautophagy
Cellular responses to stimuli: Amino acids regulate mTORC1
Gene Ontology:
Molecular function: guanyl-nucleotide exchange factor activity; molecular adaptor activity; protein binding
Biological process: cellular response to amino acid stimulus; cellular response to nutrient levels; positive regulation of TOR signaling; positive regulation of TORC1 signaling; protein localization to lysosome; regulation of cell size; TORC1 signaling
Cellular component: FNIP-folliculin RagC/D GAP; lysosomal membrane; lysosome; Ragulator complex; late endosome membrane
Genetic constraint (gnomAD): Loss-of-function variants: 11 observed, 10.06 expected, observed/expected ratio (o/e) 1.09, 90% interval 0.69 to 1.74. The synonymous counts are far from expectation, so gnomAD's model fits this gene poorly and the ratio says little. Missense variants: 123 observed, 109.36 expected, observed/expected ratio (o/e) 1.12, 90% interval 0.97 to 1.31. Synonymous variants: 68 observed, 47.59 expected, observed/expected ratio (o/e) 1.43, 90% interval 1.17 to 1.75.
Homologues: Orthologues: rabbit LAMTOR4 (99% identical), guinea pig LAMTOR4 (98% identical), rat Lamtor4 (97% identical), mouse Lamtor4 (96% identical), chimpanzee LAMTOR4 (78% identical), macaque LAMTOR4 (75% identical), dog LAMTOR4 (68% identical), tropical clawed frog lamtor4 (67% identical), zebrafish lamtor4 (66% identical), Drosophila melanogaster Lamtor4 (27% identical).
Diseases named in the same sentence as LAMTOR4 in open-access papers:
LAMTOR4 is named in the same sentence as 14 diseases in open-access papers, as found by Europe PMC text mining. Sharing a sentence is not in itself a finding about the gene and the disease. The quoted sentences say what the papers report.
Alzheimer disease (2 papers, 2023 to 2024). A progressive, neurodegenerative disease characterized by loss of function and death of nerve cells in several areas of the brain leading to loss of cognitive function such as memory and language. "LAMTOR4 has 12 transcripts and 2 GAWAS associations in GWAS catalog related to venous thromboembolism and Alzheimer disease." (PMID 37817005, 2024). "LAMTOR4 mutants reduced the number of phagocytic cells — microglia, leading to weakened phagocytosis and reduced the clearance of Aβ protein in Alzheimer's disease." (PMID 37582720, 2023).
Carpenter syndrome (1 paper, 2022). An extremely rare autosomal recessive syndrome characterized by premature closure of cranial sutures leading to cone-shaped head, fusion of the digits, and the presence of more digits than normal. "We identified MEGF8, associated with carpenter syndrome, to be downregulated in the IUO offspring while LAMTOR4, associated with the regulator complex involved in lysosomal signaling and trafficking, was found to be upregulated in the PNO groups, respectively." (PMID 35681434, 2022). "Of these, MEGF8, associated with carpenter’s syndrome, was downregulated in the IUO SVs, and LAMTOR4, a regulator of microglial lysosomes, was upregulated in the PNO SVs." (PMID 35681434, 2022).
cervical cancer (1 paper, 2025). A primary or metastatic malignant neoplasm involving the cervix. "Using genetic variants as instrumental variables, we identified key genes such as FUOM, H2BC21, LAMTOR4, and PRKCQ, which demonstrated direct effects on cervical cancer susceptibility." (PMID 40817807, 2025). "Additionally, PRKCQ and H2BC21 were significantly overexpressed in HeLa cells, whereas LAMTOR4 showed a slight but statistically significant decrease (p < 0.01), suggesting differential roles for these genes in cervical cancer biology." (PMID 40817807, 2025).
lymphoma (1 paper, 2023). A malignant (clonal) proliferation of B- lymphocytes or T- lymphocytes which involves the lymph nodes, bone marrow and/or extranodal sites. "The evaluation of the genes in association with BCR has revealed that targeting CD79A, CD79B, and LAMTOR4 as the shared genes can provide novel biomarkers for pSS progression into lymphoma." (PMID 37176092, 2023). "Thus, we suggest that the overactivation of BCR-related genes such as CD79A, CD79B, and LAMTOR4 as the shared overexpressed genes among DLBCL, pSS peripheral, and SGs could be involved in pSS progression into lymphoma and probably be responsible for the failure of Rituximab therapy." (PMID 37176092, 2023).
prostate carcinoma (1 paper, 2024). A carcinoma that arises from epithelial cells of the prostate gland. "Considering the well-established associations of PTEN (loss) and ERG (gain) with the outcomes and prognosis of prostate cancer patients, we attempted to investigate the prognostic relevance of LAMTOR4 in conjunction with PTEN or ERG." (PMID 39125671, 2024). "The data presented here supports an important and vital role for LAMTOR4 as a biomarker associated with prostate cancer progression and metastasis and with significant clinical outcome prognostic value as an individual biomarker or in association with PTEN loss/ERG expression." (PMID 39125671, 2024). "In prostate cancer, the knockdown of LAMTOR4 resulted in downregulation of beta-catenin, a key player in cell adhesion and gene transcription, and the upregulation of phospho-PTEN, a phosphorylated form of the tumor suppressor PTEN observed in our experiments." (PMID 39125671, 2024). "TCGA-PRAD data also shows LAMTOR4 mRNA expression was highly expressed in prostate cancer patients when compared to normal tissues." (PMID 39125671, 2024). "Our results revealed that LAMTOR4 is significantly overexpressed in prostate cancer tissue compared to adjacent benign tissue." (PMID 39125671, 2024). "Inhibiting components of the mTOR pathway, including LAMTOR4, might offer a strategy to inhibit tumor progression and metastasis in prostate cancer." (PMID 39125671, 2024).
rectal tumor (1 paper, 2020). "For example, rectal tumor organoids showed a diminished expression of the colorectal tumorigenesis suppressor ERBIN7 and increased expression of the mTORC1 activator LAMTOR4 and the protumorigenic gene ZFAS1." (PMID 32824266, 2020).
stomach cancer (1 paper, 2024). "LAMTOR4 expression was significantly increased in all types of cancers compared to normal tissues, except AML, skin, and stomach cancer." (PMID 39125671, 2024).
tumor (3 papers, 2024 to 2025). "On the other hand, LAMTOR4 expression positively correlated with NK cells (r = 0.37, p < 0.01) and M1 macrophages (r = 0.39, p < 0.01), suggesting its role in promoting anti‐tumor immunity." (PMID 40817807, 2025). "We further investigated the molecular mechanism involved in the LAMTOR4 knockdown and its relationship with potential tumor pathways." (PMID 39125671, 2024). "We further explored the PanCancer database to investigate LAMTOR4 gene expression in 22 types of cancers in tumor and normal tissues." (PMID 39125671, 2024). "The expression levels of LAMTOR4 showed statistically significant positive correlation with tumor cell proliferation (p = 0.002), and cellular response to hypoxia as well as DNA repair." (PMID 39125671, 2024). "Key findings include the identification of FUOM, PRKCQ, H2BC21, and LAMTOR4 as pivotal regulators of tumor progression and immune modulation, with FUOM playing a particularly prominent role in promoting cell proliferation, migration, and colony formation, as demonstrated by experimental validation." (PMID 40817807, 2025). "However, there is a considerable possibility that LAMTOR4 is directly involved in tumor cell proliferation and metastasis." (PMID 39125671, 2024). "This is in line with our observations, as the LAMTOR4 gene potentially functions as an oncogene and its expression may play a role in tumor cell proliferation and metastasis." (PMID 39125671, 2024). "The model includes PRKCQ, FUOM, H2BC21, LAMTOR4, and HCG22, along with critical clinical factors such as age, tumor grade, and tumor stage (T and N)." (PMID 40817807, 2025). "For example, there was a positive correlation with tumor proliferation signature genes, and a negative correlation with apoptosis genes due to the overexpression of LAMTOR4." (PMID 39125671, 2024).
cancer (1 paper, 2024). A tumor composed of atypical neoplastic, often pleomorphic cells that invade other tissues. "Our data indicate LAMTOR4 is crucial in cancer development and progression and impacts patients’ clinical outcomes." (PMID 39125671, 2024). "PanCancer data analysis of LAMTOR4 gene expression in 22 types of cancers showed that LAMTOR4 was significantly overexpressed in 20 types of cancers, including PCa." (PMID 39125671, 2024). "However, little is known about LAMTOR4 expression in cancer." (PMID 39125671, 2024). "As no prior studies have examined the involvement of LAMTOR4 in cancer, its role in the disease remains unclear." (PMID 39125671, 2024).
neurodegenerative disease (1 paper, 2023). A disorder of the central nervous system characterized by gradual and progressive loss of neural tissue and neurologic function. "It was shown that enhanced autophagy was associated with extended lifespan in model organisms (such as worm and mouse), and increasing evidences indicated that several genes (including LAMTOR4, LAMTOR2 and NPRL3) involved in mTOR network regulated autophagy and neurodegenerative diseases." (PMID 37582720, 2023).
LAMTOR4 also shares sentences with these, for which no sentence is quoted: Obesity (2 papers); amyloid (1); prostate adenocarcinoma (1); venous thromboembolism (1).